NUPR2 (nuclear protein 2, transcriptional regulator)
Description:
Involved in the G1 cell cycle arrest, and in a decrease in cell viability and cell proliferation. Plays a role as a negative regulator of the protumoral factor NUPR1.
Synonyms: NUPR1L; P8
Tractability: No criterion of Open Targets' tractability assessment is met for any kind of drug.
Gene: Protein-coding gene on chromosome 7 (56,114,681 to 56,116,417, reverse strand). Ensembl gene ENSG00000185290.
Subcellular location: Nucleus
Gene Ontology:
Biological process: cellular response to starvation; DNA damage response; negative regulation of cell population proliferation; negative regulation of transcription by RNA polymerase II; regulation of cell cycle; negative regulation of cell cycle; regulation of transcription by RNA polymerase II
Cellular component: nucleus
Genetic constraint (gnomAD): Loss-of-function variants: 14 observed, 7.06 expected, observed/expected ratio (o/e) 1.98. That is too few expected variants to judge how well the gene tolerates losing a copy. Missense variants: 160 observed, 125.38 expected, observed/expected ratio (o/e) 1.28, 90% interval 1.12 to 1.46. Synonymous variants: 56 observed, 52.07 expected, observed/expected ratio (o/e) 1.08, 90% interval 0.87 to 1.34.
Homologues: Orthologues: macaque NUPR2 (87% identical), dog NUPR2 (74% identical), rabbit NUPR2 (73% identical), mouse Nupr2 (72% identical), pig NUPR2 (71% identical), rat Nupr2 (69% identical), guinea pig NUPR2 (54% identical), tropical clawed frog nupr1 (28% identical), zebrafish nupr1b (26% identical), Drosophila melanogaster CG6770 (18% identical). Paralogues in human: NUPR1 (36% identical).
Diseases named in the same sentence as NUPR2 in open-access papers:
NUPR2 is named in the same sentence as 3 diseases in open-access papers, as found by Europe PMC text mining. Sharing a sentence is not in itself a finding about the gene and the disease.
NUPR2 shares sentences with these, for which no sentence is quoted: cancer (1 paper); colon cancer (1); tumor (1).